DNMT1 (DNA methyltransferase 1)
Diseases named in the same sentence as DNMT1 in open-access papers (continued):
Sharing a sentence is not in itself a finding about the gene and the disease.
atherosclerosis (continued). "The authors also observed that miR-148a/152 reversely regulates DNMT1 gene expression in the context of Hcy-accelerated atherosclerosis, and in vitro transfection of miR-148a/152 promoted lipid accumulation by silencing DNMT1 in foam cells." (PMID 36293305, 2022). "The first major epigenetic mechanism that contributes to the complexity of atherosclerosis is DNA methylation, which is catalyzed by DNA methyltransferase 1 (DNMT1) and 3b (DNMT3b) DNA methylation." (PMID 36009488, 2022). "For example, N-phthaloyl-l-tryptophan 1 (RG108), a DNMT1 inhibitor, and its maleimide derivatives can be considered as potential agents for the treatment of atherosclerosis and CAD." (PMID 34940525, 2021). "It was also reported that PPAR-γ is a target of DNMT1-regulated DNA methylation and is involved in DNMT1-mediated chronic inflammation and atherosclerosis development." (PMID 34439147, 2021). "The researchers also found that DNMT1 expression was negatively correlated to PPAR-γ expression in the peripheral monocytes of human subjects with atherosclerosis." (PMID 32309269, 2020). "DNMT1 drives the M1 polarization in atherosclerosis by directly targeting the promoter of PPAR-γ in macrophages." (PMID 29507865, 2018). "Taken together, these findings provide strong evidence that DNMT1 silencing prevents atherosclerosis by reducing endothelial proliferation and pro-inflammation in the arterial wall." (PMID 29118325, 2017). "Altogether, the strong correlation between DNMT1 expression and atherosclerosis suggests a positive contribution of DNMT1 to atherogenesis." (PMID 29118325, 2017). "Together, our results demonstrate that disturbed flow influences endothelial function and induces atherosclerosis in an mTOR/DNMT1-dependent manner." (PMID 29118325, 2017). "To gain insight into the in vivo relevance and functional implications of DNMT1 in atherosclerosis, we examined DNMT1 expression and global methylation of its substrate, DNA cytosine-5, in atherosclerotic plaques." (PMID 29118325, 2017). "Here, we determined that DNMT1-specific inhibition in arterial wall ameliorates the disturbed flow-induced atherosclerosis through, at least in part, targeting cell cycle regulator cyclin A and connective tissue growth factor (CTGF)." (PMID 29118325, 2017). "Our findings suggest that the severity and duration of atherosclerosis contributes to changes in DNMT1 expression." (PMID 27213032, 2015). "In this study, DNMT1 expression was down-regulated in atherosclerosis, MI, and IS patients (signifying hypomethylation) and positively correlated with expression of markers in TCR signaling (i.e, CD81, CD3)." (PMID 27213032, 2015). "These microarray results were used to identify novel mechanosensitive genes such as DNA methyltransferase-1 and miR-712 that play key roles in atherosclerosis." (PMID 25977794, 2014). "In addition, we also discovered that obesity-induced factors induce DNA hypermethylation at the PPARγ1 promoter via DNMT1, promoting macrophage polarization, inflammation, and the progression of insulin resistance and atherosclerosis." (PMID 41596507, 2026). "In addition to the lncRNA CDKN2B-AS1, DNMT1’s expression in foam cells is reciprocally regulated by miR-148a/152, likely playing an essential role in homocysteine-related atherosclerosis." (PMID 37947606, 2023). "The abolishment of DNMT1 in vivo can inhibit the formation of aortic disease (atherosclerosis)." (PMID 36293392, 2022). "Moreover, DNMT1 has been shown to promote activation of macrophage M1 by suppressing KLF4 expression in atherosclerosis." (PMID 34439147, 2021). "Jo and colleagues showed that DNMT1 is correlated with atherosclerosis." (PMID 31387590, 2019). "Key observations indicated that overexpressed CDKN2B-AS1 could potentially promote cholesterol efflux in atherosclerosis by downregulating ADAM10 via DNMT1-mediated ADAM10 DNA methylation." (PMID 30926762, 2019).
atherosclerosis (continued). "Consistent with observations from the three-month-HFD model, the flow-disturbance-accelerated atherosclerosis model showed up-regulated DNMT1 expression and DNA methylation in the EC layers and in the lesion regions, in comparison with those in the normal regions." (PMID 29118325, 2017). "In addition, DNMT1 expression was significantly decreased in patients with IS, atherosclerosis and MI (P=6•10−6 for atherosclerosis; P=6•10−8 for IS; P=8•10−5 for MI)." (PMID 27213032, 2015). "Thus, we subsequently tested the hypothesis that the overexpression of lncRNA CDKN2B-AS1 via binding to DNMT1 can reduce atherosclerosis and promote cholesterol efflux by downregulating ADAM10." (PMID 30926762, 2019). "Furthermore, Dnmt1, a maintenance enzyme responsible for de novo methylation, regulates the methylation status of the PPARγ promoter in macrophages, where more Dnmt1 correlates with less PPARγ gene expression levels in atherosclerosis patients’ monocytes." (PMID 30283300, 2018). "Another scientific group investigating the effect of Hcy on fatty acid binding protein 4 (FABP4) suggested that FABP4 plays a key role in Hcy mediated disturbance of lipid metabolism and that DNA methyltransferase 1 (DNMT1) may be a novel therapeutic target in Hcy-related atherosclerosis." (PMID 27932944, 2016). "In VSMCs, D-loop methylation via DNMT1 impairs mitochondrial function and decreases VSMC contraction in atherosclerosis." (PMID 37947606, 2023). "Our results indicated that DNMT1 mediates EC-SOD promoter hypomethylation to suppress its expression, and thus promoting oxidative stress and atherosclerosis induced by Hcy." (PMID 35866603, 2022). "MiR-148a, along with its participation in lipid metabolism, together with DNA methyltransferase 1 (DNMT1), regulates the expression of genes involved in the pathogenesis of atherosclerosis." (PMID 31212708, 2019). "The present study also identified that lncRNA CDKN2B-AS1 recruited DNMT1 to ADAM10 promoter region, initiated methylation and inhibited ADAM10 expression, thereby diminishing atherosclerosis and promoting cholesterol efflux." (PMID 30926762, 2019). "In support, recruitment of Dnmt1 by Ezh2 at the ABCA1 promoter is shown to transcriptionally silence ABCA1 expression, and accelerate progression of atherosclerosis." (PMID 29261844, 2017). "Maet al. found that Hcy induces extracellular-superoxide dismutase (EC-SOD) DNA hypomethylation in macrophages and that DNMT1 acts as the essential enzyme in the methyl transfer process, leading to downregulation of EC-SOD expression and increased atherosclerosis." (PMID 37021975, 2023). "DNMT1 also hypermethylates the promoter of atheroprotective Krüppel-like factor 4 (KLF4), downregulating its expression and promoting M1 macrophage inflammation and atherosclerosis." (PMID 37947606, 2023). "Increased DNMT1 in macrophages has been correlated with decreased peroxisome proliferator-activated nuclear receptor γ (PPAR-γ) and increased proinflammatory cytokines in an atherosclerosis-prone mice model as well as in atherosclerotic patients." (PMID 35563540, 2022). "Silencing of DNMT-1 by adenovirus-mediated DNMT shRNA inhibits the expressions of EC dysfunction-related proteins, including proliferating cell nuclear antigen, VCAM-1, and ICAM-1, and blocks the development of atherosclerosis." (PMID 31387590, 2019).
atherosclerosis (continued). "Their results showed that FABP4 has a very important function in lipid metabolism disturbance after Hcy treatment and also that DNA methyltransferase 1 (DNMT1; EC 2.1.1.37) could be a potential therapeutic target in Hcy-related atherosclerosis." (PMID 27775595, 2016). "DNMT1-regulated DNA methylation targets Peroxisome proliferator-activated receptor γ (PPAR-γ), and 5-aza-2′-deoxycytidine (5-Aza-Dc) may counteract infiltration and activate immune cells, exerting protective effects against atherosclerosis." (PMID 40428388, 2025). "Further, non-laminar blood flow can increase DNMT1-dependent DNA hypermethylation, reducing the expression of mechanosensitive genes, including HoxA5 and Klf3 in endothelial cells, favouring the development of atherosclerosis." (PMID 37947606, 2023). "In conclusion, Hcy may alter the DNA methylation status and DNMT1 acts as the essential enzyme in the methyl transfer process to disturb the status of EC-SOD DNA methylation, leading to decreased expression of EC-SOD and increased oxidative stress and atherosclerosis." (PMID 35866603, 2022).
lupus (53 papers, 2010 to 2025). "DNA methyltransferase 1, a key enzyme mediating CpG island methylation, has been implicated in lupus pathogenesis through aberrant epigenetic regulation." (PMID 41457558, 2025). "For instance, in systemic lupus erythematosus, aberrations of DNA methylation are associated with DNMT1 expression, while significantly lower amounts of DNMT1 and DNMT3A transcripts are observed." (PMID 39334883, 2024). "Partly due to the deficiency and inhibition of DNA methyltransferase 1 (Dnmt1), an enzyme crucial to maintain DNA methylation, the DNA of lupus CD4+ T cells is generally hypomethylated." (PMID 31575058, 2019). "In lupus, miR-126 is significantly higher than healthy controls and the expression level is conversely linked to DNMT1 activity." (PMID 28785369, 2017). "There are varieties of microRNAs applied as lupus biomarkers, including DNMT1-related microRNAs, renal function-associated microRNAs, microRNAs involved in the immune system, and microRNAs for phenotype classification." (PMID 28785369, 2017). "DNA hypomethylation of T cells from active lupus patients or lupus mice has been detected, as a result of decreased expression and activity of the enzyme DNMT1 due to deficient Ras-MAPK pathway signaling." (PMID 28785369, 2017). "Variants in DNMT1 have been identified as risk factors for disease including systemic lupus erythematosus." (PMID 21347319, 2011). "The deficiency of DNMT1 will result in the progress of lupus." (PMID 33282947, 2020). "The downstream consequence of diminished DNMT1 activity is global DNA hypomethylation in CD4+ T cells from lupus patients." (PMID 41376628, 2025). "In this regard, HYD induced a lupus-like phenotype through the inhibition of the ERK pathway, causing downregulation of DNMT1." (PMID 36927767, 2023). "Reduced Dnmt1 and/or Dnmt3a/b expression has been correlated with the global DNA hypomethylation in the human lupus." (PMID 38153351, 2023). "It has been reported that DNMT1 and/or DNMT3a/3b expressions were significantly decreased in human lupus PBMCs and CD4+ T cells when compared to those of healthy controls, which correlated with the global DNA hypomethylation in the cells." (PMID 34062726, 2021). "It has been reported that the upregulation of miR-126 in lupus T cells was inversely correlated with the DNMT1 protein expression level." (PMID 34062726, 2021). "In systemic lupus erythematosus (SLE) model Fas-deficient-MRL/lpr mice, exosome transplantation rescued the osteoporotic phenotype by the Fas/miR-29b/Dnmt1/Notch cascade." (PMID 33542737, 2021). "miR-148a and miR-126 were upregulated in lupus T cells and targeted DNMT1 directly, whereas upregulated miR-21 and miR-29b targeted DNMT1 indirectly." (PMID 34062726, 2021). "In CD4+ T cells from lupus patients, low activity of DNMT1 has been observed after activation of AhR by UVB." (PMID 32899152, 2020). "Another inspiring observation is that miR-126 has been reported to regulate DNA methylation in lupus T cells by targeting DNMT1, supporting the idea that lupus T cells are switched on by DNA hypomethylation via miRNAs." (PMID 32849827, 2020). "We found that upregulated miR-126 promotes the expression of CD11a and CD70 in lupus CD4+ T cells via inhibiting DNMT1-mediated DNA methylation." (PMID 32308657, 2020). "MiR-21 affects indirectly DNA methyltransferase 1 (DNMT1) expression in a lupus-prone murine model, by targeting RAS guanyl releasing protein 1 (RASGRP1), linked to autoimmune disease." (PMID 30322050, 2018). "miR-21, miR-126, and miR-148a are three DNA methylation-associated miRNAs that aimed at binding to a certain methylation machinery in SLE, and this was accomplished by directly or indirectly targeting lupus-related gene DNA methyltransferases (DNMT1)." (PMID 28785369, 2017).
lupus (continued). "We traced the lupus T cell DNA methylation defect to a failure to upregulate DNA methyltransferase 1 (Dnmt1) as the cells enter mitosis." (PMID 28620656, 2017). "The results indicate that PP5 is a previously undescribed regulator of T cell Dnmt1 expression as well as the expression of methylation sensitive genes that contribute to lupus pathogenesis." (PMID 28239687, 2016). "These genes were selected because they are over-expressed by T cells experimentally demethylated in vitro by treatment with Dnmt1 inhibitors and in T cells from patients with active lupus." (PMID 28239687, 2016). "We therefore tested if PP5 is overexpressed in CD4+ T cells from patients with lupus and if PP5 decreases T cell Dnmt1 expression and causes overexpression of genes normally suppressed in T cells by DNA methylation." (PMID 28239687, 2016). "Although numerous miRNAs are found to be abnormally expressed in T cells, certain miRNA target lupus-related gene expression, including IL-10, IL-17, and DNMT1." (PMID 25988383, 2015). "More inspiring is that miR-126 has been reported to regulate DNA methylation in lupus T cells by targeting DNMT1, supporting the idea that lupus T cells are switched on by DNA hypomethylation via miRNAs." (PMID 25988383, 2015). "Hydralazine was shown to induce in vivo murine lupus via preventing DNMT1 upregulation by inhibition of the ERK (and potentially other) signaling pathways in T cells." (PMID 25566322, 2014). "Overexpression of several miRNAs, such as miR-21, -148a, -126, and -29b, is reported to affect DNA methylation machinery of lupus CD4+ T cells by targeting DNMT1." (PMID 24991086, 2014). "Certain studies have observed that T cells from patients with active lupus have diminished DNMT1 mRNA levels." (PMID 23596493, 2013). "In fact it has been demonstrated that T cells from patients with active lupus have hypomethylated DNA, due to decreased DNMT1 levels and activity." (PMID 21941583, 2012). "The study also showed that treating lupus patient T cells ex vivo with inhibitors of miR-21 and miR-148a could increase DNMT1 levels and partially reverse DNA hypomethylation, bringing the methylation status of genes closer to that in healthy T cells." (PMID 41376628, 2025). "However, unchanged Dnmt1 expression and even increased Dnmt3a/b gene expression have also been identified in human lupus PBMCs or CD4+ T cells in different studies, despite the consistency of DNA hypomethylation in these lupus cells." (PMID 38153351, 2023). "Moreover, inhibiting hsa_circ_0012919 corrects the DNA hypomethylation of CD70 and CD11a in lupus CD4+T cells by promoting DNMT1 activity." (PMID 32308657, 2020). "Subsequent studies demonstrated low Dnmt1 levels in T cells from patients with active lupus." (PMID 30764520, 2019). "Indeed, in lupus patients, a decrease of DNMT1 was mediated by the overexpression of miRNA-21 (microRNA) and miRNA-148a that control the DNMT1 gene expression." (PMID 29449903, 2018). "Furthermore, miRNA-148a can contribute to DNA hypomethylation in lupus CD4+ T cells by repressing DNA methyltransferase 1 expression." (PMID 30036399, 2018). "However, authors in other studies found that T cells or PBMCs from patients with lupus have exhibited a reduced DNMT1 mRNA levels." (PMID 28349196, 2017). "Some authors suggest that a defect in DNMT1 may be the primary reason of abnormal DNA methylation in CD4+ T cells from lupus patients." (PMID 28349196, 2017). "Increased miR-21, miR-148a, and miR-126 in lupus CD4+ T cells reduced the expression of DNMT1 directly or indirectly, leading to DNA hypomethylation and overexpression of autoimmune-associated methylation-sensitive genes such as CD70, lymphocyte function-associated antigen 1 (LFA-1), and CD11a." (PMID 27070142, 2016).